MIR544B (microRNA 544b)
Synonyms: hsa-mir-544b
Safety:
Unwanted effects reported when the protein is acted on. In parentheses: how it was acted on, where the effect was seen, and who reports it.
nausea and vomiting (source: ClinPGx)
Gene: MicroRNA gene on chromosome 3 (124,732,439 to 124,732,516, forward strand). Ensembl gene ENSG00000265981.